MAPK4 (mitogen-activated protein kinase 4)
Diseases named in the same sentence as MAPK4 in open-access papers (continued):
Sharing a sentence is not in itself a finding about the gene and the disease.
colitis (1 paper, 2025). Inflammation of the colon. "Furthermore, by using TNF-α to establish an inflammatory model in Caco-2 cells, it has been further confirmed that SPDD can indeed alleviate colitis in mice by downregulating the expression of MAPK4." (PMID 40238233, 2025). "Overall, our study demonstrated that SPDD reversed colonic inflammation in colitis mice through the MAPK4/AKT pathway and might be a promising candidate for UC intervention." (PMID 40238233, 2025). "Furthermore, SPDD weakened the interaction between MAPK4 and AKT, resulting in a decrease in the phosphorylation level of AKT, thereby reducing the expression of IL-6, IL-1β, iNOS, and COX-2, and alleviating colitis (p < 0.05)." (PMID 40238233, 2025).
Crohn disease (1 paper, 2018). A gastrointestinal disorder characterized by chronic inflammation involving all layers of the intestinal wall, noncaseating granulomas affecting the intestinal wall and regional lymph nodes, and transmural fibrosis. "In recent studies targeting Crohn’s disease in humans, it was evidenced that the kinase MAP3K4 (Mitogen-activated protein kinase 4) was responsible for variation of IL1A, regardless of variation in TLR activation." (PMID 30161141, 2018).
Insulin resistance (1 paper, 2016). Increased resistance towards insulin, that is, diminished effectiveness of insulin in reducing blood glucose levels. "Up-regulated MAPK4 expression can lead to insulin resistance, and MAPK4 overexpression inhibits insulin-stimulated glucose uptake by negatively regulating the insulin signal-transduction pathway." (PMID 27846294, 2016).
osteosarcoma (1 paper, 2022). A usually aggressive malignant bone-forming mesenchymal neoplasm, predominantly affecting adolescents and young adults. "At the same time, MAPK4 is highly expressed in osteosarcoma and inhibits cell proliferation and migration by activating the JNK/p38 signalling pathway." (PMID 36618768, 2022).
Papillary Thyroid Carcinoma (1 paper, 2022). "Additionally, we found that MAPK4 could promote the proliferation of papillary thyroid cancer cells and mediate the effect of miR-576-5p on the proliferation of TPC-1 cells." (PMID 36618768, 2022).
parasite infection (1 paper, 2023). "To examine the role of host MAPK4 on parasite infection, we generated MAPK4-deficient (MAPK4-KO) human intestinal adenocarcinoma HCT-8 cells by using CRISPR/Cas9-genome editing." (PMID 36658270, 2023). "We revealed diverse effects of host MAPK4 on parasite infection; however, underlaying mechanisms of MAPK4 signaling are yet to be investigated." (PMID 36658270, 2023). "Future investigation for those ligands or agents involved in the possible interference by parasites for manipulating host MAPK4 will facilitate potential drug targets for inhibiting parasitic infection and growth in infected mammals." (PMID 36658270, 2023).
rectal tumors (1 paper, 2019). "CYT-high rectal tumors on the other hand, had recurrent deletions at loci 3p21.31 (RHOA), 5q22.2 (APC), 10q26.2 (MGMT), 14q32.2 (AKT1, EIF5, YY1), 18q21.2 (SMAD4, MAPK4), and a single amplification in 7p15.3 (STK31)." (PMID 31429779, 2019).
virus infection (1 paper, 2016). "These include the co-receptor SERKs, BAK1 and SERK1, and the MAPK4 negative regulator, in addition to common effects of non-viral PTI that are also elicited during virus infection." (PMID 28105028, 2016).
tumor (39 papers, 2013 to 2025). "MAPK4, a kinase involved in cellular signal transduction, has been linked to angiogenesis and tumor growth, with higher expression correlating with poor prognosis." (PMID 40260244, 2025). "Our studies collectively identify a novel mechanism promoting PDK1 protein expression and further advance our knowledge of the molecular mechanism underlying the tumor-promoting activity of MAPK4, an emerging novel therapeutic target for human cancers." (PMID 37531320, 2023). "In cells within the tumor microenvironment, Mapk4 can be upregulated as a protective mechanism against the cytotoxic effects of M1 macrophages, for example, by activating prosurvival signaling pathways." (PMID 40942182, 2025). "MAPK4 promotes tumor cell proliferation, migration, survival, and drug resistance through several signaling pathways, such as AKT-mTOR, GATA2-AR, and PDK1." (PMID 39863600, 2025). "Further analysis showed that MAPK4 silencing inhibited the proliferation and migration abilities of HUVECs cultured in tumor cell supernatant, which was accompanied with increased transduction of the ERK1/2 pathway." (PMID 38947754, 2024). "MAPK4 is a direct target of miR-767-5p; by targeting and regulating the MAPK4 pathway, miR-767-5p is capable and proficient in promoting tumor growth as well as progression." (PMID 38672402, 2024). "In contrast, MAPK4 overexpression both promoted cell growth and rendered tumor cells at least partially resistant to Alpelisib and GSK2334470 co-treatment." (PMID 37531320, 2023). "To resolve the paradox of the inconsistent functions of MAPK4 in vivo and in vitro, we explored the possibility that the tumor microenvironment is involved in MAPK4 downregulation-induced invasion." (PMID 36797541, 2023). "We also performed an analysis of immune tumor infiltration levels among GBM with different somatic copy number alterations in MAPK4." (PMID 36999945, 2023). "Our previously reported PI3K-independent MAPK4-AKT signaling axis provides a direct mechanism for MAPK4 driving tumor cell resistance to PI3K blockade." (PMID 37531320, 2023). "Consistently, MAPK4-overexpressing BGC-LM cells educated by the tumor microenvironment had a reduced capacity for cell invasion compared with control cells." (PMID 36797541, 2023). "The results indicated that MAPK4 was predominantly expressed in tumor cells, other than immune cells or other non‐tumor cells." (PMID 36999945, 2023). "This new MAPK4-PDK1 axis alone lacks vigorous tumor-promoting activity but cooperates with our previously reported MAPK4-AKT axis to promote tumor growth." (PMID 37531320, 2023). "We have previously demonstrated that AKT activation is essential for supporting MAPK4 tumor-promoting activity." (PMID 37531320, 2023). "The ability of MAPK4 to bypass PI3K for AKT activation potentially provides a direct mechanism regulating tumor sensitivity to PI3K inhibition." (PMID 35017531, 2022). "The ability of MAPK4 to directly activate AKT suggests that elevated MAPK4 expression should reduce tumor sensitivity to PI3K blockade." (PMID 35017531, 2022). "As an atypical member of the MAPK family, the physiological and pathological functions of mitogen-activated protein kinase 4 (MAPK4) in tumours have gradually begun to gain attention." (PMID 36618768, 2022). "In conclusion, expression and functional studies suggest that both miR-433 and miR-127 have tumor suppressive function in GC via targeting MAPK4 and KRAS respectively." (PMID 23880861, 2013). "Previous studies have demonstrated that overexpression of MAPK4 promotes tumor progression." (PMID 40238233, 2025). "Moreover, ECM stiffness can increase the sensitivity of tumor cells to genotoxic agents by activating MAPK4/6/7 and increasing ubiquitin phosphorylation, thereby inhibiting ubiquitin signaling and DNA repair following DNA double-strand breaks." (PMID 40685383, 2025).
tumor (continued). "At the same time, we have identified a number of genes whose hypomethylation, potentially associated with an increase in gene transcription, may be involved in tumor progression Interestingly, a hypomethylation in MAPK4/6 emerged." (PMID 40640872, 2025). "Interestingly, MAPK4 was demonstrated to promote tumours through direct and specific activation of AKT/mTOR via an alternative pathway without dependence on PI3K/PDK1." (PMID 40845073, 2025). "Furthermore, our observation that MAPK4 KO mice exhibit impaired humoral immune responses extends the understanding of MAPK4’s function beyond its previously reported roles in tumor biology and highlights its significance in immune regulation." (PMID 39863600, 2025). "Accordingly, co-blockade of AKT and PDK1 largely blocks MAPK4 tumor-promoting activity." (PMID 37531320, 2023). "Together, these data suggest that PDK1 may only partially mediate MAPK4 activities in promoting tumor cell growth and resistance to PI3K blockade." (PMID 37531320, 2023). "PDK1 clearly partially mediates MAPK4 tumor-promoting activity." (PMID 37531320, 2023). "Finally, overexpression of PDK1 appeared less potent than MAPK4 in rescuing the growth of these MAPK4-KO cells/xenografts, which are consistent with the notion that PDK1 only partially mediates MAPK4 tumor-promoting activity." (PMID 37531320, 2023). "While ectopic expression of AKT1-DD alone showed some activity, co-expression of MAPK4D254A further enhanced cell growth, and the activity of co-expressed MAPK4D254A and AKT1-DD largely recapitulated WT MAPK4 tumor-promoting activity in the proliferation assays." (PMID 37531320, 2023). "Our identified PI3K-independent MAPK4-AKT signaling axis may provide a pathway for MAPK4-high TNBC tumor intrinsic resistance to PI3K inhibitors." (PMID 35017531, 2022). "It seems that MAPK4 may exert different effects on different tumours, with anti- or pro-oncogenic effects." (PMID 36618768, 2022). "Interestingly, there were differences in tumour size, with rates of MAPK4 positivity in PTC (>1 cm), PTC (<1 cm), and normal thyroid tissues of 63.31%, 25.78%, and 9%, respectively." (PMID 36618768, 2022). "Recently, research on MAPK4 in the field of tumours has received increasing attention." (PMID 36618768, 2022). "However, MAPK4 was found to be downregulated in pancreatic adenocarcinoma and identified as a tumour suppressor." (PMID 36618768, 2022). "Since MAPK4 can directly activate AKT to promote tumor growth, we examined whether MAPK6 also activates AKT." (PMID 34767444, 2021). "Therefore, circ-MAPK4 can be seen as a therapeutic target as knockdown of circ-MAPK4 allows miR-125a-3p to regain its tumor suppressive function." (PMID 34162394, 2021). "In vitro and in vivo studies supported the tumor suppressor role of circ_0000190 that seems to exert its function by sponging miR-767-5p, preventing the repression of its validated target MAPK4; the anti-tumor activity of circ_0000190 was confirmed in mouse models." (PMID 32019064, 2020). "Silencing of circ-MAPK4 generated notable decrease in rate and tumor size of xenografts." (PMID 31992303, 2020). "Our results revealed that the ability of circ_0000190 to protect against MM was inherited through repression of miR-767-5p, and miR-767-5p might be a tumor drive through targeting MAPK4." (PMID 30728056, 2019). "The findings reported in this study are of tremendous clinical significance due to the clarification of the impact of circ_0000190 on miR-767-5p/MAPK4 could serve as a basis for the development of predictive biomarkers of tumor emergence and prevention in MM." (PMID 30728056, 2019).
tumor (continued). "Additionally, hypomethylation of MAPK4/6 in recurrent tumors has been associated with more aggressive cellular behavior, supporting the idea that epigenetic changes in TMZ-resistant cells create a permissive environment for tumor growth and progression." (PMID 40640872, 2025). "Finally, these data also support that PDK1 partially mediates MAPK4 tumor-promoting activity." (PMID 37531320, 2023). "Notably, MAPK4 expression was positively correlated with tumor infiltration by macrophages, Th1 cells, Th17 cells, follicular helper T cells (TFHs), neutrophils and eosinophils but negatively correlated with infiltration by CD8+ T cells, plasmacytoid DCs (pDCs) and T helper cells." (PMID 36999945, 2023). "Additionally, we investigated whether the MAPK4-AKT signalling pathway mediates the role of miR-576-5p in promoting tumour proliferation, migration, and invasion." (PMID 36618768, 2022). "Collectively, these data suggest that MAPK4 both PDK1-independently and -dependently regulates tumor cell response to PI3K blockade, and MAPK4 overexpression renders cancer cells at least partially resistant to PI3K and PDK1 co-blockade." (PMID 37531320, 2023). "To further evaluate PDK1’s function in mediating MAPK4 tumor-promoting activity, we overexpressed PDK1 in the MAPK4-KO SUM159 and MDA-MB-231 cells." (PMID 37531320, 2023). "Based on the concerted actions of MAPK4-AKT and MAPK4-PDK1 signaling axis in driving MAPK4 tumor-promoting activities, we tested and confirmed that co-blockade of AKT and PDK1 effectively represses MAPK4-induced cancer cell growth." (PMID 37531320, 2023). "To confirm the role of MAPK4 in the regulation of TAM activation, we used flow cytometry to gate the total macrophage population from orthotopic tumor tissues by F4/80 staining and examined CD206 expression in this population." (PMID 36797541, 2023). "These suggest that MAPK4 activates additional signaling cascade(s) beyond PDK1 and AKT for full tumor-promoting activity." (PMID 37531320, 2023). "We previously reported that MAPK4, an atypical MAPK, can PI3K-independently promote AKT activation and tumor growth." (PMID 37531320, 2023). "It was found that circ-MAPK4 positively regulated the MAPK pathway by acting as a sponge to miR-125a-3p, a miRNA that plays a tumor-suppressive function by inhibiting the MAPK pathway." (PMID 34162394, 2021). "Overexpression of MAPK4 leads to the activation of its known substrate, mitogen-activated protein kinase-activated protein kinase 5 (MK5), which is a marker of tumor onset at a very early stage of development, and initiates cell migration." (PMID 34337053, 2021). "Since both the canonical PI3K/PDK1 pathway and our recently identified MAPK4 pathway can independently regulate AKT activation, the tumor-promoting activities of endogenous MAPK6 are likely to be context dependent." (PMID 34767444, 2021). "The results suggest a synergistic inhibitory effect of MAPK4 knockout and PARP1 inhibitor on tumor growth in vivo." (PMID 32711558, 2020). "A recent report demonstrated that MAPK4 activates protein kinase B (AKT) in a phosphatidylinositol 3-hydroxykinase (PI3K)-independent manner and promotes cell proliferation and xenograft tumor growth." (PMID 32711558, 2020). "The tumor suppressor roles of miR-433 and miR-127 in GC cells were mediated by inhibition of KRAS and MAPK4, respectively." (PMID 23880861, 2013). "In contrast, knockdown of PDK1 leaves the MAPK4-AKT signaling axis largely intact in the MAPK4-overexpressing cells, which may account for the partially maintained tumor cell growth." (PMID 37531320, 2023). "In this case, dual activation of AKT and PDK1 is necessary but not sufficient for the full tumor-promoting activity of MAPK4." (PMID 37531320, 2023). "Collectively, these data suggest that MAPK4 promotes MNK1/2-mediated eIF4E S209 phosphorylation; however, unexpectedly, eIF4E S209 phosphorylation does not play a notable role in MAPK4 promotion of PDK1 protein expression or tumor growth." (PMID 37531320, 2023).
tumor (continued). "According to previous studies, MAPK4 promotes tumor progression by activating the AKT/mTOR pathway in a noncanonical manner." (PMID 36999945, 2023). "MiR‐125a‐3p, a tumor‐suppressive miRNA by targeting p38/MAPK, was found to increase after suppressing circ‐MAPK4, and it could be pulled down by circ‐MAPK4." (PMID 36705414, 2023). "The overexpression of MAPK4 has been reported to promote tumor progression via noncanonical activation of AKT/mTOR signaling." (PMID 36797541, 2023). "miR-125a-3p, exhibited tumor-suppressive action by modulating the p38/MAPK pathway, which was elevated when circ-MAPK4 was inhibited and could be brought down by circ-MAPK4." (PMID 35883576, 2022). "It was shown that the MAPK4 and AKT signalling pathways are related in a variety of tumours." (PMID 36618768, 2022). "Base on the proposed tumor suppressor role of p38/MAPK, phosphorylation of p38/MAPK will activate its effect in inhibiting cell proliferation, which is consistent with what’s shown and what happens with circ-MAPK4 silencing." (PMID 31992303, 2020). "Lastly, co-expression of MAPK4D254A and AKT1-DD only partially recapitulated the tumor-promoting activity of WT MAPK4 in the soft-agar assays, suggesting that MAPK4 activation of additional signaling cascade beyond PDK1 and AKT may be important to promote tumor cell anchorage-independent growth." (PMID 37531320, 2023). "Finally, despite robust activities in blocking eIF4E phosphorylation at S209, none of the 2 MNK1/2 inhibitors exhibited notable tumor-inhibiting activities in any of the tumor cell lines we tested, including the MAPK4-low and MAPK4-KO cancer cell lines." (PMID 37531320, 2023). "Finally, miR-125a-3p, a miRNA exhibited tumor-suppressive function through impairing p38/MAPK pathway, which was increased by inhibiting circ-MAPK4 and could be pulled down by circ-MAPK4." (PMID 31992303, 2020). "Inhibition of MAPK4 downregulated the level of AKT phosphorylation independent of the PI3K pathway and improved tumor sensitivity to the PI3K inhibitor Alpelisib." (PMID 40200093, 2025). "Notably, overexpression of MAPK4 can drive AKT phosphorylation independent of phosphoinositide 3-kinase (PI3K), thus neutralizing the anti-tumor activity of the PI3K inhibitor in NSCLC cells." (PMID 40200093, 2025).